NANOG (Nanog homeobox)
Diseases named in the same sentence as NANOG in open-access papers (continued):
Sharing a sentence is not in itself a finding about the gene and the disease.
progeria (2 papers, 2021 to 2023). "To examine the effects of NANOG in progeric skeletal muscle, we crossed LAKI mice (L) and Tet-On-NANOG mice to give rise to progeny with a fast-aging progeria phenotype capable of NANOG expression upon doxycycline (Dox) administration (LN)." (PMID 36797255, 2023). "NANOG expression was induced in the TA muscle of 10 months old (Col1a1tetO-NANOG/+;ROSA26rtTA/+;LmnaG609G/+) progeria mice by intramuscular injection of Atridox, which polymerized in vivo and released Dox for a period of 2 to 3 weeks." (PMID 34516892, 2021). "Since NANOG reversed many of the metabolic indicators of progeria cells we tested whether NANOG could have similar effects in vivo." (PMID 36797255, 2023). "Most notably, NANOG decreased the prevalence of SA-β-Gal–positive myogenic progenitors and restored the number of these Pax7+ progenitors in the skeletal muscle of LAKI progeria mice in vivo." (PMID 34516892, 2021).
rectal cancer (2 papers, 2017 to 2019). A primary or metastatic malignant neoplasm that affects the rectum. "Analysis of the rectal cancer dataset showed upregulation of stemness markers, NANOG and LGR5." (PMID 28689994, 2017).
skin papilloma (2 papers, 2015 to 2017). A benign papillary neoplastic growth on the skin composed of epithelial cells and a fibrous stalk. "Here, we show that inducible overexpression of NANOG in mouse skin epithelia favours the malignant conversion of skin papillomas induced by chemical carcinogenesis, leading to increased SCC formation." (PMID 25988972, 2015). "In addition, evidence was also provided to support that NANOG plays an active role in vivo, promoting malignant conversion of skin papillomas into carcinomas in transgenic mice." (PMID 28894270, 2017).
skin squamous cell carcinoma (2 papers, 2015 to 2023). A carcinoma arising from the squamous cells of the epidermis. "Together, these results demonstrate that NANOG can promote malignant progression to skin squamous cell carcinoma." (PMID 25988972, 2015).
small cell carcinoma (2 papers, 2019 to 2021). A neuroendocrine carcinoma composed of small malignant cells which are often said to resemble "oat cells" under the microscope. "The newly available LuCaP 93 small cell carcinoma was found to express these scTF, but with lower NANOG." (PMID 31146720, 2019). "Cancer de-differentiation transforms luminal-like (differentiated) adenocarcinoma into less luminal-like and more stem-like (undifferentiated) small cell carcinoma through a sequential activation of stem cell transcription factors (scTF) POU5F1, LIN28A, SOX2 and NANOG." (PMID 34911496, 2021). "Previously, we reported the presence of scTF LIN28A, NANOG, POU5F1 and SOX2 in a small cell carcinoma patient-derived xenograft (PDX) line LuCaP 145.1 but absent in adenocarcinoma PDX lines." (PMID 31146720, 2019). "Newly available non-adenocarcinoma/small cell carcinoma PDX LuCaP lines were analyzed for expression of stem cell transcription factors (scTF) LIN28A, NANOG, POU5F1, SOX2, which are responsible for reprogramming or de-differentiation." (PMID 31146720, 2019).
thyroid cancer (2 papers, 2020 to 2025). "To reveal the role of LINC00162 and sorafenib treatment in regulating the stemness of thyroid cancer cells, we evaluated the expression of SOX2, NANOG, CD133, and CD44 in B-CPAP cancer cells." (PMID 40804316, 2025).
adenoma (1 paper, 2017). A neoplasm arising from the epithelium. "Interestingly, OCT4 and NANOG expression did not significantly differ between AhR+/+ adenomas and AhR−/− carcinomas, a result that probably reflects a differential function of both genes in regeneration after acute toxicity with respect to liver carcinogenesis." (PMID 28874739, 2017).
Ascites (1 paper, 2014). Accumulation of fluid in the peritoneal cavity (between the layers of the peritoneum that lines the abdomen). "The expression of CD117, Oct4 and JAGGED was significantly up in paclitaxel-treated ascites tumor cells, while there was a trend in the increased expression of EpCAM, CD44 and NANOG but it was not significant compared to untreated control." (PMID 24886434, 2014).
B-cell lymphoma (1 paper, 2017). "In accordance with these findings, the expression of stem cell markers (NANOG and SOX2) was significantly higher in B-cell lymphoma cells survived after phenylbutyrate and doxorubicin treatment than control cells." (PMID 27911272, 2017).
benign prostate hyperplasia (1 paper, 2015). "A clear upregulation of NANOG occurs following the progression from benign prostate hyperplasia to high grade PIN (HGPIN) and from HGPIN to PC; NANOG upregulation during PC progression is stimulated by HIF-1α." (PMID 26593949, 2015).
cerebrovascular disease (1 paper, 2023). "miRNA 145 is established to suppress stem cell pluripotency markers, such as OCT4, SOX2, and NANOG, and increases levels of SMA in SMCs; thus, disruption of this miRNA likely causes MMD-like cerebrovascular disease through a similar mechanism to ACTA2 p.R179 variants." (PMID 37886459, 2023).
cervical (1 paper, 2025). "Further studies with larger numbers of patients and molecular insights should focus on the diagnostic and prognostic significance of NANOG and SOX2 in the entire process of cervical carcinogenesis." (PMID 40272007, 2025).
cervical squamous cell carcinoma (1 paper, 2025). A squamous cell carcinoma arising from the cervical epithelium. "NANOG and SOX2 expression was evaluated immunohistochemically on 40 patients: in 10 cases each of low-grade SIL (LSIL), high-grade SIL/CIN, grade 2 (HSIL/CIN 2), HSIL/CIN, grade 3 (HSIL/CIN 3), cervical squamous cell carcinoma (CSCC) and their adjacent non-dysplastic squamous epithelium." (PMID 40272007, 2025).
colorectal adenoma (1 paper, 2025). An adenoma that arises from the colon or rectum. "In other cancers, IL‐33 is induced and activated early in the development of colorectal adenomas and regulates the expression of the stemness genes NANOG, NOTCH3, and OCT3/4." (PMID 40860436, 2025).
Cornelia de Lange syndrome (1 paper, 2023). A rare syndrome characterized by low birth weight, delayed growth, intellectual disabillity, behavioral problems, and a distinctive facial appearance (thin, arched eyebrows, low set ears, small teeth, and small nose). "NANOG and NIBPL are essential for early heart development, and mutation of NIBPL causes Cornelia-de Lange syndrome with a spectrum of congenital heart malformations including BAV." (PMID 37961530, 2023).
cyst (1 paper, 2017). A sac-like closed membranous structure that may be empty or contain fluid or amorphous material. "Co-staining of OCT4 with other pluripotency markers—NANOG and SOX2—confirms that the columnar side of the asymmetric cyst is composed of undifferentiated, epiblast-like cells, resembling the embryonic disc at one pole of the human amniotic sac." (PMID 28785084, 2017).
diffuse large B-cell lymphoma (1 paper, 2023). "Comprehensive microarray analysis has revealed that diffuse large B-cell lymphoma (DLBCL) with higher expression of CSC markers, such as NANOG, is highly progressive." (PMID 36831547, 2023).
epilepsy (1 paper, 2022). A brain disorder characterized by episodes of abnormally increased neuronal discharge resulting in transient episodes of sensory or motor neurological dysfunction, or psychic dysfunction. "Noteworthy, the two KDM5C subgroups showed significant changes in NANOG expression in the subset of patients without epilepsy or with the wild-type IDH1/2 genotype or with MGMT methylation, while significant OCT4 change was found in the subset of patients with the wild-type IDH1/2 genotype." (PMID 36142158, 2022).
esophageal tumors (1 paper, 2023). "Moreover, in the induced esophageal tumors of Otud6b cKO mice, the expression of β‐TrCP and the differentiation marker CK13 was decreased, and the levels of SOX2 and NANOG were increased." (PMID 37038094, 2023).
Ewing sarcoma (1 paper, 2016). A small round cell tumor that lacks morphologic, immunohistochemical, and electron microscopic evidence of neuroectodermal differentiation. "There is an established relationship between EWS-FLI1 and the pluripotency genes SOX2, OCT4, and NANOG in Ewing sarcoma." (PMID 27074562, 2016). "Cancer stem cells in Ewing sarcoma are involved in chemo resistance, with in vitro musculoskeletal sarcoma stem cells expressing SOX2, OCT3/4 and NANOG." (PMID 27074562, 2016).
gastric MALT lymphoma (1 paper, 2023). "OLFM4 and NANOG could be positive and negative predictive markers, respectively, for eradication therapy efficacy against gastric MALT lymphoma that is negative for both API2-MALT1 and Hp infection." (PMID 36831547, 2023).
gestational trophoblastic disease (1 paper, 2023). "It has been postulated that NANOG is involved in the pathogenesis of gestational trophoblastic disease, likely through its effect on apoptosis and cell migration." (PMID 37198424, 2023).
hepatoblastoma (1 paper, 2016). Hepatoblastoma (HB) is a malignant hepatic tumor and is the most common pediatric liver cancer. "Functional experiments using Hep3B and Huh7 HCC cell lines and HepG2 hepatoblastoma cell line showed that forced YAP1 overexpression was associated with a significant increase in the viability and mRNA levels of the stem cell markers CD133, NANOG, and OCT-3/4 in the three cell lines." (PMID 27359056, 2016).
Hutchinson-Gilford progeria syndrome (1 paper, 2021). "We further confirmed improvements in the senescence hallmarks in vivo using a mouse model of Hutchinson-Gilford progeria syndrome, where expression of NANOG in the skeletal muscle restored the number of resident myogenic progenitors and induced formation of eMyHC+ myofibers." (PMID 34516892, 2021).
hyperlipidemia (1 paper, 2022). "Building upon these benchmark data, we sought to explore the impact of prolonged hyperlipidemia as well as the effect colchicine-based therapy on a variety of atheroprotective (Klotho, HOXA5, NOTCH1, and OCT4) and proatherogenic (HIF1a, SOX2, BMP4, and NANOG) genes." (PMID 36362692, 2022).
hypopharyngeal tumors (1 paper, 2020). "Positive NANOG expression was significantly associated with node positive (N+) tumors (p = 0.003) and hypopharyngeal tumors (p = 0.019), and was also more frequent in poorly differentiated (p = 0.084) and advanced stage (p = 0.204) tumors." (PMID 32635524, 2020).
intestinal neuroendocrine tumors (1 paper, 2015). "The present study conducted immunohistochemical analyses for DCLK1 and the stemness marker, NANOG, in human intestinal neuroendocrine tumors (NETs), as their expression had not been previously investigated in these tumors." (PMID 26622789, 2015).
ischemia (1 paper, 2022). A hypoperfusion of the BLOOD through an organ or tissue caused by a PATHOLOGIC CONSTRICTION or obstruction of its BLOOD VESSELS, or an absence of BLOOD CIRCULATION. "Furthermore, the ischemic brain regions exhibiting higher frequencies of NANOG-expressing cells coincided with the brain regions undergoing active neurogenesis, such as the SVZ and SGZ, further supporting the physiological significance of NANOG induction in ischemia-induced neuronal regeneration." (PMID 36376495, 2022).
kidney cancer (1 paper, 2015). Primary or metastatic malignant neoplasm involving the kidney. "We first compared the expression of the OCT4, NANOG, LIN28, and KLF4 stem cell transcription factors between the parental kidney cancer cell lines and their sphere derivatives." (PMID 25011053, 2015).
laryngeal squamous cell carcinoma (1 paper, 2020). A squamous cell carcinoma that arises from the larynx. "NANOG has been found overexpressed in different cancer types, including OSCC and laryngeal squamous cell carcinoma (LSCC)." (PMID 32635524, 2020).
laryngeal tumors (1 paper, 2020). "While either NANOG expression or double-positive expression of NANOG and SOX2 were significantly correlated with improved survival rates in patients harboring pharyngeal tumors, none of these factors showed any impact on the clinical outcome of patients with laryngeal tumors." (PMID 32635524, 2020). "Our results show that NANOG protein expression is frequent in HNSCC and emerges as an independent predictor of better clinical outcome, specifically in pharyngeal but not laryngeal tumors." (PMID 32635524, 2020). "Thus, NANOG expression, and to a lesser extent SOX2, specifically predicted good prognosis in patients with pharyngeal but not laryngeal tumors." (PMID 32635524, 2020).
leukoplakia (1 paper, 2024). A white patch or plaque on a mucous membrane that cannot be characterized clinically or pathologically as any other disease. "Therefore, our study uncovers the potential application of NANOG expression as an early surrogate marker for predicting malignant conversion in leukoplakia and a potential prognostic indicator in OSCC." (PMID 38558704, 2024).
liver disease (1 paper, 2023). "By contrast, control CD133-/CD49f- cells expression levels for KRT19, CD133, NANOG, SOX2, OCT4, and TLR4 were independent of IVIG (immune serum from people with HBV+ or HCV+ liver disease) or HBIG incubation." (PMID 37744383, 2023).
lymphoblastic leukaemia (1 paper, 2018). "In addition to its well-known functions in lymphoblastic leukaemia and a number of cancers, PBX1 was also found to promote hESC self-renewal by corporately binding to the regulatory elements of NANOG with KLF4." (PMID 30217220, 2018).
male infertility (1 paper, 2023). The inability of the male to effect fertilization of an ovum after a specified period of unprotected intercourse. "Among them, miRNAs (has-miR-3127-5p and has-miR-3184-5p), lncRNAs (AL356488.2 and AL645608.3) and TFs (NANOG and HEY1) as the key regulatory factors of PRM2, FSCN3 and TEKT2, were predicted significantly associated with male infertility." (PMID 37891374, 2023).
malignant glioma (1 paper, 2021). A grade III or grade IV glioma arising from the central nervous system. "Taken together, the results strongly suggest that h-NANOG regulates CXCR4 expression in human malignant gliomas." (PMID 34638956, 2021).
mesothelioma (1 paper, 2020). A usually malignant and aggressive neoplasm of the mesothelium which is often associated with exposure to asbestos. "The poor differentiation of human mesothelioma is associated with enhanced expression of NANOG, which can be induced by mitochondrial ROS." (PMID 32664372, 2020). "Since the pleomorphic mesothelioma is less differentiated than the tubulopapillary, this indicates that NANOG expression increases with the loss of differentiation of mesothelioma." (PMID 32664372, 2020). "Mitochondria of mesothelioma cells have a large capacity to form ROS and thereby upregulate NANOG, leading to dedifferentiation of mesothelioma." (PMID 32664372, 2020). "Mitochondria-targeted ROS scavenger mitoTEMPO abolished the effect of 5 μM antimycin A on NANOG, verifying that mitochondrial ROS induced NANOG expression and thereby partial dedifferentiation of mesothelioma cells." (PMID 32664372, 2020). "One of our key findings is that mitochondrial ROS induces NANOG protein expression in mesothelioma, which emphasizes the key role of mitochondria in the maintenance of undifferentiated state of human mesothelioma cells." (PMID 32664372, 2020). "We demonstrated that, upon stimulation, mesothelioma cell mitochondria generated ROS that upregulated NANOG protein." (PMID 32664372, 2020). "Poorly differentiated histological subtype of mesothelioma had higher expression of NANOG than the subtype with the greater degree of differentiation." (PMID 32664372, 2020). "In conclusion, human mesothelioma displays enhanced expression of NANOG, SOX2 and phosphorylated AKT proteins, while elevated NANOG expression correlates with poor differentiation of human mesothelioma." (PMID 32664372, 2020). "This further demonstrates that increased NANOG expression correlates with poor differentiation of mesothelioma." (PMID 32664372, 2020). "We designed this study to determine the expression of the most important pluripotency genes and proteins, OCT4, NANOG and SOX2 in human mesothelioma and to investigate its association with the PI3K-AKT-BCL2 pathway." (PMID 32664372, 2020). "Compared to normal mesothelium, mesothelioma exhibited higher expression of NANOG and SOX2 proteins and lower expression of POU5F1, NANOG and SOX2 genes." (PMID 32664372, 2020). "We demonstrated that human mesothelium and mesothelioma express NANOG and SOX2 proteins and POU5F1, NANOG and SOX2 genes." (PMID 32664372, 2020). "NANOG protein expression was elevated in less differentiated samples of human mesothelioma." (PMID 32664372, 2020). "Since upregulation of several pluripotency factors induces cellular reprogramming and dedifferentiation in Yamanaka’s experiment, such induction of NANOG in our experiment indicates that partial reprogramming and dedifferentiation of mesothelioma cells can be driven by mitochondrial ROS." (PMID 32664372, 2020). "Moreover, poorly differentiated histological subtype, pleomorphic mesothelioma showed greater expression of NANOG than the better-differentiated tubulopapillary subtype." (PMID 32664372, 2020). "Thus, our results indicate that increased activity of PI3K-AKT pathway is likely associated with observed upregulation of NANOG and SOX2 in human mesothelioma." (PMID 32664372, 2020). "Since protein expression is directly related to cellular phenotype and therefore more relevant than gene expression, our results indicate that mesothelioma has upregulated NANOG and SOX2 pluripotency factors compared to mesothelium, its tissue of origin, indicating dedifferentiation of mesothelioma." (PMID 32664372, 2020). "Our study demonstrates that NANOG and SOX2 genes and proteins are expressed in human mesothelium and mesothelioma and they may have diagnostic potential." (PMID 32664372, 2020). "Our observation that NANOG is more expressed in human mesothelioma subtype with poor differentiation status further supports the role of NANOG expression in regulation of differentiation status of human mesothelioma." (PMID 32664372, 2020).